ABCB6 (ATP binding cassette subfamily B member 6 (LAN blood group))
Diseases named in the same sentence as ABCB6 in open-access papers (continued):
Sharing a sentence is not in itself a finding about the gene and the disease.
glioblastoma (2 papers, 2019 to 2024). The most malignant astrocytic tumor (WHO grade IV). "Modulation of ABCB6 expression levels in human glioblastoma cells resulted in a concomitant change in cadmium sensitivity." (PMID 31053883, 2019). "Third, we provide evidence that ABCB6 modulates the cadmium sensitivity of human glioblastoma cells." (PMID 31053883, 2019). "The functional relevance of ABCB6 in Cd sensitivity was further evaluated in SNB-19 glioblastoma cells." (PMID 31053883, 2019). "Although we find that the endogenous ABCB6 protein is confined to the endolysosomal compartment of SNB-19 glioblastoma cells, it may be argued that the precise intracellular localization can only be established with the discovery of a matching physiological function." (PMID 31053883, 2019).
prostate adenocarcinoma (2 papers, 2021 to 2023). "Another study identified five glycolysis-related mRNAs (GYS2, STMN1, PPFIA4, KDELR3, and ABCB6) which were associated with patients experience biochemical recurrence (BCR) after radical prostatectomy (RP) in patients with prostate adenocarcinoma." (PMID 34489401, 2021).
aniridia (1 paper, 2013). Aniridia is a congenital ocular malformation characterized by the complete or partial absence of the iris. "Heterozygous missense mutations (p.L811V and p.A57T) in ABCB6 caused iris coloboma, aniridia, chorioretinal coloboma." (PMID 24224009, 2013).
autism (1 paper, 2010). Persistent deficits in social interaction and communication and interaction as well as a markedly restricted repertoire of activity and interest as well as repetitive patterns of behavior. "Although the association of Abcb6 with autism has yet to be investigated, numerous validated missense mutations of the Abcb6 gene have been reported (National Center for Biotechnology Information 2010)." (PMID 20576582, 2010).
erythroleukemia (1 paper, 2007). Acute erythroid leukemia characterised by the presence of at least 50% erythroid precursors and at least 20% myeloblasts in the bone marrow. "Mouse erythroleukemia (MEL) cells were used as model to study the role of ABCB6 and ABCB7 during cellular differentiation." (PMID 17726528, 2007).
familial pseudohyperkalemia (1 paper, 2023). "Recently, ABCB6 has been reported to be responsible for familial pseudohyperkalemia, a disorder related to DHSt37." (PMID 36864026, 2023).
high blood pressure (1 paper, 2022). "ABCB6, member of adenosine triphosphate (ATP)‐binding cassette (ABC) transporters, was identified as correlated with arterial stiffness, a risk factor linked with vascular ageing and high blood pressure." (PMID 35094491, 2022).
meningioma (1 paper, 2023). A generally slow growing tumor attached to the dura mater. "Protein expression of ABCB6, ABCG2, FECH and CPOX was found in meningioma tissue and was correlated with fluorescence (p < 0.05, each), whereas this was not confirmed for mRNA expression." (PMID 36612300, 2023). "ABCB6, ABCG2, FECH and CPOX are expressed in meningioma tissue and are related to fluorescence." (PMID 36612300, 2023). "In samples from the bulk tumor, the median expression scores for ABCB6, ABCG2, FECH and CPOX were 9 (range: 2–12), 8 (range: 3–12), 9 (range: 1–12) and 9 (range: 1–12), respectively, and expression was similar comparing grade 1 and 2/3 meningiomas (p > 0.05 for each)." (PMID 36612300, 2023).
protein misfolding diseases (1 paper, 2024). "The chaperone activity of 4-PBA, established in other protein misfolding diseases, suggests L356P may be misfolded compared to ABCB6 WT23,24." (PMID 39557842, 2024).
cancer (140 papers, 1996 to 2026). A tumor composed of atypical neoplastic, often pleomorphic cells that invade other tissues. "The main function of ABCB6 is regulating porphyrin biosynthesis; recently, it has been reported to be associated with multidrug resistance and the development and progression of various cancers." (PMID 35123420, 2022). "Furthermore, the acquisition of chemoresistance in HTLA-Chr cells is associated with the overexpression of ABCB6 (ATP binding cassette transporter 6), a mitochondrial drug transporter which is also correlated with the multidrug resistance in several cancer cells." (PMID 27683112, 2016). "Glycolysis-regulating genes such as SOX9, ABCB6 and ENO1, were associated with metabolic reprogramming essential for cancer progression." (PMID 39920655, 2025). "Specifically, the expressions of PEPT1 and ABCB6 were upregulated in dormant cancer cells, whereas that of ABCG2 was downregulated." (PMID 33790399, 2021). "Since siABCB6 reduced PpIX accumulation in dormant cancer cells, it is suggested that increased expression of ABCB6 contributed to PpIX accumulation increase in dormant cancer cells." (PMID 27857072, 2016). "There is a possibility that the HCCs overexpressing ABCB6 harbor cancer stem cells responsible for intrahepatic metastasis." (PMID 23483087, 2013). "We have preliminary data that ABCB6 expression is more significantly increased in cancer stem cell-like sphere cells as compared to other ABC transporters (unpublished data)." (PMID 23483087, 2013). "Several of the top SNPs are in genes associated with PCa or PCa processes, including MKI67 (rs8473), PCSK6 (rs80278342), ABCB6 (rs60322991), and TCHP (rs11068997); or other cancer-associated processes, including GGA2 (rs1135045), H1-5 (rs11970638), and COL15A1 (rs2075662)." (PMID 38052806, 2023). "Furthermore, to examine the contribution of ABCB6 on dormant cancer cells, we used RNAi technology to suppress the expression of ABCB6 in the high cell density-2D cultured cells." (PMID 27857072, 2016). "The identification of ABCB6 as an HMT-1 orthologue links ABCB6 to heavy metal-related diseases, such as neurodegenerative conditions, dysfunction of the digestive tract and cancer." (PMID 31053883, 2019). "Similar to ABCB6, ABCC1, and ABCC3 are also capable of effluxing chemotherapeutics of broad function including anti-cancer functions." (PMID 30655622, 2019). "We further analyzed the differential expression of DPYSL4, HOMER1, ABCB6, CENPA, CDK1, STMN1 in cancer and adjacent tissues, and found that compared with adjacent tissues, the six genes in 309 HCC tissues were significantly up-regulated (P<0.01)." (PMID 31790363, 2019). "In dormant cancer cells, transporter expressions of PEPT1, ALA importer, and ABCB6, an intermediate porphyrin transporter, were upregulated and that of ABCG2, a PpIX exporter, was downregulated." (PMID 27857072, 2016). "Further gene-targeting experiments are needed to disclose the role of ABCB6 in IHR of HCC, especially with regard to the role of cancer stem cells in metastasis." (PMID 23483087, 2013). "In dormant cancer cells, PEPT1 and ABCB6 were upregulated, and ABCG2 was downregulated." (PMID 33790399, 2021). "Although, the molecular mechanisms by which ABCB6 expression is related to chemotherapy resistance or cancer progression are unknown, ABCB6-high malignant cancers are considered to be suitable targets for 5-ALA PDD/PDT because ABCB6-high cancer cells are thought to accumulate PpIX." (PMID 31083682, 2019).
tumor (63 papers, 1998 to 2025). "Cox regression analysis provided a novel finding that tumor ABCB6 mRNA levels can be an independent risk factor for IHR of HCC after surgery." (PMID 23483087, 2013). "The univariate analysis showed that ABCB6 mRNA level, ABCB6 DNA methylation level and tumor histological grade were significant risk factors for IHR after surgery." (PMID 23483087, 2013). "Thus, ABCB6 expression could promote multiple survival strategies that are usually the hallmark of tumor development and progression." (PMID 22808084, 2012). "Overall, the enhanced fluorescence is associated with low expression of ferrochelatase, overexpression of ABCB6, low expression of ABCG2, the accumulation of heme synthesis-related metabolites caused by IDH1 mutations, and the tumor microenvironment." (PMID 39518115, 2024). "As expected, most tumor samples displayed expression of ABCB6, ABCG2, FECH and CPOX in our study, and expression was strongly correlated with fluorescence." (PMID 36612300, 2023). "Five GRGs (ABCB6, ANKZF1, B3GAT3, KIF20A and STC2) were dysregulated in tumor samples and were independently associated with the prognosis of HCC." (PMID 35123420, 2022). "There are many biological effects of ABCB6, such as protection against oxidative stress, acquired resistance, and the potential promotion of tumor proliferation." (PMID 33952718, 2021). "The relationship between tumor ABCB6 mRNA level and shorter DFS time was specific for HCV-related HCC but not HCV-unrelated HCC (data not shown)." (PMID 23483087, 2013). "HCCs with IHR within a year showed 3.1-fold (P=0.050) higher ABCB6 mRNA levels compared to those from corresponding adjacent non-tumor liver tissues." (PMID 23483087, 2013). "Evaluation of modulators of ABCB6 activity would pave the way toward a more complete understanding of the significance of this transport process in tumor cell growth, proliferation and therapy-related drug resistance." (PMID 22808084, 2012). "ABCB6 expression is upregulated in many tumor cell lines and in liver tumors where it appears to promote cell survival and tumor growth and proliferation." (PMID 22808084, 2012). "Furthermore, consistent with previous reports, the ABCB6 mRNA levels were increased in HCCs compared to those in adjacent non-tumor liver tissues." (PMID 23483087, 2013). "ABCB6 gene is amplified in tumor cells with acquired chemotherapeutic resistance." (PMID 22808084, 2012). "Relationship between transferrin receptor (TFR), ABCB6, and ABCB7 mRNA expression and response to artesunate (ART) in tumor cell lines of the NCI drug screening panel." (PMID 17726528, 2007). "In addition to mRNA and DNA methylation levels of ABCB6, tumor histological differentiation grade, UICC tumor stage and number of primary tumors were examined as variables, because Kaplan-Meier curves for DFS showed significant differences (data not shown)." (PMID 23483087, 2013). "Therefore, this study was the first proposed the relationship between ABCB6, IPO7, TIMM9, and ACAT1 and HBV, and they may be related to tumor progression in HBV-induced HCC as FZD7." (PMID 36685852, 2022). "Notably, unspecific low-to-moderate expression of ABCB6 (median score 8, range: 8–9), ABCG2 (median score 3, range: 1–4), FECH (median score 4, range: 1–8) and CPOX (median score: 1, range: 0–1) was also found in all nine fluorescent cortex samples lacking tumor invasion." (PMID 36612300, 2023).
infection (12 papers, 2011 to 2025). The state of being infected such as from the introduction of a foreign agent such as serum, vaccine, antigenic substance or organism. "Taken together, these results demonstrate that Lan null cells are not inherently resistant to infection by Plasmodium parasites, and suggest that P. falciparum may have a unique reliance on ABCB6 as a host factor during invasion." (PMID 30271928, 2018).
metabolic disease (2 papers, 2019 to 2020). A congenital disorder (due to inherited enzyme abnormality) or acquired (due to failure of a metabolically important organ) disorder resulting from an abnormal metabolic process. "The network was categorized as “Small Molecule Biochemistry,” “Hematological Disease,” and “Metabolic Disease,” which were composed of down-regulated genes that were listed in the top 2 and 3 networks of A.SW mouse spleen: Gata1-related genes and transporter genes (Abcb6, Slc25a39, and Slc25a37)." (PMID 30941144, 2019).
adenocarcinoma (1 paper, 2012). A common cancer characterized by the presence of malignant glandular cells. "Heterologous expression of rat Abcb6 in a human adenocarcinoma cell line resulted in a subcellular localization confined to the endo/lysosomal compartment." (PMID 22655043, 2012).
psychiatric disorder (1 paper, 2025). A disorder characterized by behavioral and/or psychological abnormalities, often accompanied by physical symptoms. "Moreover, emerging evidence suggests that ABC transporter genes, including ABCB1 and ABCB6, influence susceptibility to psychiatric disorders like MDD." (PMID 40559416, 2025).
ABCB6 also shares sentences with these, for which no sentence is quoted: leukemia (7 papers); cystic fibrosis (6); ovarian carcinoma (6); prostate carcinoma (5); acute myeloid leukemia (4); Alzheimer disease (4); adrenoleukodystrophy (3); colon cancer (3); esophageal cancer (3); genetic disorders (3); liver cancer (3); anemia (2); Brain Tumor (2); cardiovascular disease (2); cervical cancer (2); dengue (2); depression (2); myeloma (2); neuroblastoma (2); neurological disease (2); retinal degeneration (2); schizophrenia (2); Stargardt disease (2); thyroid carcinoma (2); acute lymphoblastic leukemia (1); age-related macular degeneration (1); Arthritis (1); arthropod-borne viral infections (1); autoimmune disease (1); B-cell lymphoma (1).
A further 47 diseases each share a sentence with ABCB6 in 1 paper.